CD4 (CD4 molecule)
Diseases named in the same sentence as CD4 in open-access papers (continued):
Sharing a sentence is not in itself a finding about the gene and the disease.
asthma (continued). "Our data shows that overproduction of IL-18 protein in the lungs increases pulmonary inflammation accompanied with IL-13 producing CD4+ T cells, and results in increasing AHR in this mouse asthma model." (PMID 23382928, 2013). "Previous studies have shown that CD4+CD25+ Foxp3+ Treg cells inhibit the development and progression of allergic diseases including asthma." (PMID 23617952, 2013). "Our results are in accordance with other authors that have reported changes in frequency of CD4+CD25+ T cells and CD4+CD25+FOXP3+ regulatory T cells in atopic diseases, such as asthma, rhinitis, and atopic dermatitis." (PMID 24368924, 2013). "Although treatment with ACA did not inhibit B cell activation, as assessed by CD79α expression, our results show that ACA is effective at reducing populations of CD4+ Th cells and CD8+ cytotoxic T cells in the lungs of mice with OVA-induced asthma." (PMID 23451048, 2013). "Compared with control group, the ratio of peripheral blood NKT and CD4+NKT cells was significantly decreased (P < 0.01) and was elevated in SIT asthma group (P < 0.05), respectively, but it was still less than the normal control group (P < 0.01)." (PMID 23008731, 2012). "Expressions of SOCS3 and SOCS5 mRNA were analyzed by real-time quantitative PCR in peripheral CD4 T cells from adult patients with NAEB, asthma and healthy controls." (PMID 21765854, 2011). "In humans affected by asthma, FOXP3 protein expression within CD4+CD25high T-cells is significantly decreased compared to controls." (PMID 21843342, 2011). "CD4+ T helper type 2 (TH2) cytokines such as IL-4, IL-5 and IL-13 play a critical role in inducing allergy and asthma." (PMID 22014099, 2011). "Percentage proportions of CD4+ T cell staining positively for IL-2, IL-4, IL-10, IL-13, IFN-γ, and TNF-α in unstimulated whole blood were similar in children with asthma compared to healthy controls." (PMID 21197090, 2010). "A direct link between CD4+CD25+FoxP3+Tregs and suppression of AHR in asthma has now been demonstrated in vivo." (PMID 19769993, 2010). "Cells with regulatory potential such as CD4+CD25+FoxP3Tregs and γδT cells are also an attractive target for asthma therapy." (PMID 19769993, 2010). "In fact, treatment with inhaled glucocorticoids reduces the expression of the activation markers CD25 and HLA-DR in both CD4+ and CD8+ T-cell subsets in peripheral blood of patients with asthma." (PMID 18315837, 2008). "Naive CD4+ T cells undergo differentiation into TFH cells primarily under the influence of the transcription factor Bcl6, and accumulating evidence suggests that TFH cells, rather than Th2 cells, predominantly regulate IgE antibody class switching in asthma." (PMID 41568067, 2026). "In terms of neuroimmune interactions, IL‐5 from ILC2 and CD4+ T cells directly stimulates VIP secretion from pulmonary nociceptors, and VIP in turn activates ILC2 and CD4+ T cells, forming a positive feedback loop that amplifies Type 2 inflammation in OVA‐ and HDM‐induced asthma mouse models." (PMID 41415714, 2025). "Regarding asthma, CHI3L1 plays a key role in CD4+ T cell polarization and Th2 inflammation." (PMID 41154593, 2025). "Applying T-REX analysis to blood specimens from RV-challenged young adults with and without asthma revealed expansion of multiple CD4+ and CD8+ populations after infection." (PMID 40337866, 2025). "In type-2 high asthma, the number of inflammatory cells, including neutrophils, cDC, CD4 T cells, macrophages, and B cells did not change in Sema3E KO mice compared to WT counterparts." (PMID 40512736, 2025). "Major cytokines involved in asthma include IL4, IL5, and IL13 derived from CD4+ T cells type II." (PMID 40468357, 2025). "Integrated single‐cell RNA sequencing analysis of asthma PBMCs and AD CSF revealed IL7R may utilize the MIF‐CD74‐CXCR4 pathway to complete crosstalk between CD4 T cells and macrophages and contribute to AD disease development." (PMID 40951943, 2025).
asthma (continued). "In summary, a higher frequency of CD4+ CRTH2+ TEM and TCM Th2 cells was associated with T2 features independent of asthma status, representing a common T2‐feature‐associated signal." (PMID 40965120, 2025). "Similarly, a case from Italy involved an active smoker who was followed up due to asthma and HIV infection, was under viral suppression, and was hospitalized with a diagnosis of influenza A with a CD4 T lymphocyte count of 876 cells/mm3." (PMID 40260188, 2025). "However, the percentage of CD4 + T-cells was significantly reduced in the BPD group compared to the preterm, asthma, and healthy control groups (p < 0.05 for all)." (PMID 38336805, 2024). "Interestingly, CD4+ TRMs are highly expressed in mice with RSV infection or asthma, whereas they act differently in RSV-infected patients and asthma patients." (PMID 39632661, 2024). "Allergic responses are triggered and maintained by an imbalance among CD4+ Th cells, specifically Th2 cells, therefore, we speculated that CD226 may play a regulatory role in the progression of asthma." (PMID 39349422, 2024). "The inhibition of miR-145-5p in T CD4+ cells from patients with asthma promoted an enhanced percentage of IFN-γ+ CD4+ T cells by regulation of RUNX3; thus, miR-145-5p can modulate the Th1/th2 balance in asthma." (PMID 38337625, 2024). "Thus, type 2 CD4 + T cells are involved in asthma pathogenesis, whilst the role of CD8 + T cells has been suggested to balance the responses of CD4 + T cells through the secretion of Interferon-γ IFN-γ." (PMID 38336805, 2024). "Oddly, the CD4+ concept is highly important to the asthma class despite not being a source for asthma samples." (PMID 38468193, 2024). "Besides CD4+ effector T cells, also CD8+ effector T cells play an important role in the pathogenesis of asthma." (PMID 38757128, 2024). "For example, a Chinese study conducted on a small group of asthmatic patients with and without asthma showed decreased CD4+ CD25+ FOXP3+ Treg levels and lower FOXP3 mRNA expression in asthmatic patients compared to healthy children." (PMID 36981683, 2023). "In addition to asthma, acupuncture can be effective in treating IBS and other diseases by regulating the differentiation of CD4+ T cells." (PMID 37090714, 2023). "Compared to CD4+ T cells, there has been less research on CD8+ T cells in children with asthma." (PMID 37893483, 2023). "Although the critical role of CD4+T cells in the physiopathology is indisputable, recent evidence suggests that CD8+T cells may also be involved in asthma." (PMID 35769905, 2022). "Allergic response in an ovalbumin (OVA)-induced asthma model was not altered by CD4-specific gene deletion of Ptch1, which points out the activation of the non-canonical Hh pathway in CD4 T-cells." (PMID 35681469, 2022). "We demonstrated here for the first time that compared to non-smoking asthma patients, smokers with asthma had increased frequencies of ILC3s in the airway along with increased frequencies of memory-like ILC3s (CD4+CD45RO+ILC3s) in the peripheral blood." (PMID 35789151, 2022). "In the absence of Cul5, CD4+ T cells became overly sensitive to IL-4 which contributed to asthma pathogenesis." (PMID 35589717, 2022). "Whether the effect of IL6R on asthma arise from the modulatory role of IL6 on the immune response or a more direct effect of for example, sIL‐6R on CD4 T cells or airway epithelial cells is still unresolved." (PMID 36434743, 2022). "Given that VSTM4 reduces IFN-γ and IL-2 produced by T cells and inhibits naïve CD4+T cell differentiation into Th1 cells, VSTM4 may contribute to a relative predominance of Th2 inflammation over Th1 inflammation in asthma." (PMID 36076228, 2022). "Asthma-related airway remodeling was reduced by miR-451a overexpression, which was been shown to target ETS1, while miR-451a downregulation promotes differentiation of CD4+ T Cells towards Th2 cells through ETS1 upregulation in childhood asthma." (PMID 36172292, 2022).
asthma (continued). "In addition, suppression of miR-21 by intranasal administration of the antagomir improved asthma symptoms including airway inflammation and BHR, inhibited Th2 polarization of CD4+/CD8− cells, and altered cytokine levels in BAL fluid." (PMID 36172292, 2022). "The CD4+CD45RO+ILC3 frequencies in the peripheral blood also correlated negatively with the pulmonary function indices but not the asthma control indices." (PMID 35789151, 2022). "Jurkat cells inducibly overexpressing FOXP3 for 2 days (FOXP3 2-day cells) are similar to CD4+CD25+CD127−/low T cells from subjects without asthma and FOXP3 5-day cells are similar to Tregs from asthmatic subjects." (PMID 34072455, 2021). "Data on the frequency of Foxp3 Treg cells in murine experimental asthma are not easily compared, since they either lack nonallergic control mice and Foxp3 intracellular staining on CD4+CD25+ cells or use only one mouse strain." (PMID 34924814, 2021). "This study identified a novel role for GITRL expressed by DCs as a positive regulator of CD4+ T cells responses in asthma, which implicates that GITRL inhibitors may be a potential immunotherapy for asthma." (PMID 33557842, 2021). "Moreover, this TCM attenuation of Ccl5 was observed in both CD4+ and CD8+ T cell populations following experimental asthma induction in Nf1OPG mice." (PMID 34880260, 2021). "There was a correlation of FKBP51 and Ki-67 expression in CD4+ T-lymphocytes among both obese (r = 0.75, p < 0.01) and nonobese (r = 0.67, p = <0.01) participants with asthma." (PMID 34721414, 2021). "Moderate-severe asthma patients display increased numbers of CD4+CD103+ TRM in their airways and vaccine-enhanced disease in children with formalin-inactivated RSV is driven by TH2 CD4+ memory cells that induce excessive inflammation." (PMID 34603321, 2021). "CD4+ T cell-derived Th1/Th2 imbalance is an initiating factor in ozone exacerbated asthma through PVT1-miR-15a-5p/miR-29c-3p signaling, and miR-15b-5p is considered a biomarker for identifying patients with asthma chronic obstructive pulmonary disease overlap." (PMID 34566492, 2021). "Further, there was a significant increase in phosphorylated ERK1/2 (pERK1/2) protein in hydrogen peroxide (H2O2)-treated CD4+CD25high cells in adults with asthma compared with those without asthma." (PMID 34072455, 2021). "Unsupervised clustering analysis identified a cluster of a CD4+ T-lymphocyte subset-expressing FKBP51 and Ki-67 that was more prevalent in obese participants with asthma (2.6% of CD3+ T-lymphocytes) compared with normal weight participants (1.1% of CD3+ T-lymphocytes)." (PMID 34721414, 2021). "The mean of circulating CD4+CCR6+CRTh2+cells in children diagnosed with or without asthma was 1.6 %±0.8 and 0.8 %±0.6 %, respectively, and was significantly higher in children diagnosed with asthma (p < 0.01)." (PMID 34090369, 2021). "In view of the role of GITRL expressed on DCs in CD4+ T cell differentiation, we asked whether GITRL could impact the differentiation of CD4+ T cells in asthma." (PMID 33557842, 2021). "In contrast, ERK1/2 phosphorylation in CD4+CD25high T cells from adult subjects without asthma was observed only at high dose H2O2 (10 mM) treatment." (PMID 34072455, 2021). "To specifically dissect the contribution of GRK2 in regulating T cell responses during asthma, we generated the CD4 Cre+ GRK2fl/fl mice (that lacked GRK2 in T cells) and exposed these mice to HDME." (PMID 35386975, 2021). "In asthma, non-apoptotic eosinophils are prominent, and CD4+ T cells are more evident than CD8+ T cells." (PMID 32752252, 2020). "Using an ovalbumin murine model of asthma, all isoforms of type III IFNs were shown to alleviate allergic airway disease by reducing eosinophilia, decreasing type 2 cytokines, and modulating lung dendritic cell and CD4 + T cell functionality." (PMID 33101299, 2020).
asthma (continued). "One study revealed that under dexamethasone stimulation, CD4+ T cells from patients with steroid-resistant asthma failed to induce IL-10 synthesis." (PMID 32054098, 2020). "To confirm these findings, in a second cohort of subjects from the Asthma Bio-Repository for Integrative Genomic Exploration (ABRIDGE, Nasmathics = 300, Nhealthy = 122), we investigated the mRNA expression of NIP45 in peripheral blood CD4+ T cells." (PMID 31666531, 2019). "In summary, our study results demonstrated that placenta-derived MSCs could suppress the proliferation of CD4+ T cells and CD8+ T cells in all children and suppress the activation of CD4+ T cells and CD8+ T cells in children with asthma." (PMID 31673233, 2019). "In previous publications we suggested that “% of CD4+CRTh2+T cells” and “% of CD14++CD16+PAR-2+ monocytes” may be good biomarkers of asthma severity." (PMID 31168305, 2019). "Regarding T helper cells, we discovered that the activation of CD4+ T cells was significantly lower in the children with asthma treated with MSCs than in those not treated with MSCs." (PMID 31673233, 2019). "In our study, we also found that CD4+ T cell proliferation was significantly lower in children with asthma who received MSC treatment than in those who did not receive MSC treatment." (PMID 31673233, 2019). "Current common asthma therapeutics (including corticosteroids) were not able to affect the frequency of CCR4+CCR7+ memory CD4+ T cell subsets." (PMID 29507584, 2018). "Although the course of M. tuberculosis infection, like Brucella infection, is mainly controlled by IFN-γ-producing CD4+ T cells in mice, we observed that asthma sensitization does not affect M. tuberculosis multiplication in the lungs." (PMID 30147700, 2018). "Secreted IL-17 in splenic CD4+ T cells was significantly increased in the neutrophils-dominant asthma group compared to the conventional asthma group, but IL-4 was not obviously different in the neutrophilic group compared to the conventional group." (PMID 30150897, 2018). "Due to the heterogeneity of asthma phenotypes and clinical variation, we next investigated whether the increase of CCR7+ memory CD4+ T cells is a common feature of different asthma subtypes." (PMID 29507584, 2018). "Our findings indicate that all children, independent of their asthma status, have a competent CD4+ T‐cell recall response to RV‐A and RV‐C." (PMID 29124902, 2018). "However, another study reported that CRTH2+ CD4+ T cells are unlikely to have a significant involvement in the pathogenesis of asthma in patients, although asthma patients have increased CRTH2+ CD4+ T cells in both blood and BAL fluid." (PMID 29507584, 2018). "Th17 levels were elevated in splenic CD4+ T cells from the neutrophils-dominant asthma group compared to the conventional asthma group, but Th2 cell levels were not significantly different between the two groups." (PMID 30150897, 2018). "In addition, the same group recently showed that GLI activity is induced in multiple leukocytes in a murine model of asthma and that expression of GLI2R decreases the recruitment of CD4+ Th2 cells to the allergic lung." (PMID 29682088, 2018). "Specifically, in response to allergen-induced asthma and intestinal helminth infection, CD4+ T-cells of Bcl11bfl/fl dLck-iCre mice failed to efficiently differentiate into Th2 cells, despite the fact that they expanded normally." (PMID 29700302, 2018). "In our studies, no changes were observed in the CD3+CD4+ T cell populations in mediastinal lymph node tissue after induction of asthma with ovalbumin." (PMID 28646903, 2017). "In lymphocytes, miR-15a, miR-15b, and miR-20a are downregulated in CD4+ T cells from atopic pediatric patients with asthma, compared to atopic and non-atopic controls." (PMID 28785260, 2017).
asthma (continued). "In reference, to the results of cellular immune function test, there is an improved cellular immune function in asthma patients, presenting an increase of CD3, CD4, CD8, and decrease of CD4/CD8 in T-cell subset, an increase of erythrocyte immune RBC-C3bR, and reduction of RBC-IC." (PMID 28328807, 2017). "Our results show that CD4+ CD25+ Foxp3+ T cell percentages were lower in the BALF of mice with asthma than in the BALF of control mice, illustrating that CD4+ CD25+ Foxp3+ Treg levels are diminished in the lungs of mice with asthma." (PMID 28729731, 2017). "The absolute numbers of CD3+CD4+ cells in asthma patients were not significantly different from control group but were lower than in COPD group and ACOS group (p2-3 = 0.000010, p3-4 = 0.000165)." (PMID 27660519, 2016). "Next, we compared HDM-stimulated and unstimulated CD4 T cells in HDM-sensitized subjects without asthma." (PMID 26922672, 2016). "Again, intake of active vitD3 by asthma patients led to an increased expression of TLR9 but not other TLRs by IL-10 secreting CD4+ T cells." (PMID 27506771, 2016). "We subsequently confirmed that maintenance of regulatory T cell (Treg cell) numbers in asthma patients with CEP may inhibit EGPA development via the action of cytokines, such as IL-10 and IL-2, produced by CD4+CD25+ and CD4+CD25− T cells, respectively." (PMID 26714881, 2015). "Glucocorticoids have been suggested to amplify the IL-2-dependent expansion of FOXP3+CD4+CD25+ T cells in vivo, increase FOXP3 expression by Tregs in patients affected by asthma, and restore the impaired suppressive function of Tregs in patients with relapsing multiple sclerosis." (PMID 26379673, 2015). "The pathogenesis of asthma involves several cellular and non-cellular factors including Th2 and Th17 CD4+ T cells as well as B cells in addition to circulating factors such as IL-4, IL-5, IL-13 and many others." (PMID 26169874, 2015). "CD4+CD45RBlow cells, as Tm, were obtained by magnetic-activated cell sorting and flow cytometry from the spleens of BALB/c mice with ovalbumin (OVA)-induced asthma." (PMID 26075017, 2015). "CD4+CD25+ Tregs are impaired quantitatively and functionally and also play a protective role in suppressing airway eosinophilic inflammation and the development of airway hyperreactivity in asthma." (PMID 25246732, 2014). "The role of CD4+IL-17+ cells in pathogenesis of asthma is further supported by the presence of a negative correlation with FEV1." (PMID 25132806, 2014). "To test this, we adoptively transferred naive CD4+ T cells from DO11.10.Rag1−/− and DO11.10.Rag1−/−Cblb−/− mice into WT BALB/c recipients, and then immunized with OVA at 100 μg/ml in alum, which is the dose used to induce asthma." (PMID 24508458, 2014). "It will be interesting to determine whether CD4 TRM cells are established and maintained within the lung in mouse models of allergic asthma and their role in asthma pathogenesis and also in maintaining the hyper-responsive condition in the tissues." (PMID 25071787, 2014). "Analysis of PBMC revealed a significantly increased percentage of CD4 + CD25 + CD127lo/- T cells in children with asthma compared to non-asthmatics." (PMID 23347774, 2013). "Moreover, the Cortex Mori Radicis extract was found to enhance CD4+CD25+Foxp3+ regulatory T cells and suppress Th2 cytokines, thereby improving asthma symptoms." (PMID 23843865, 2013). "The present study demonstrates that BUD, an inhaled corticosteroid widely used for the management of bronchial asthma, controls asthma inflammation modulating ICOS, cell survival, Foxp3 and IL-10 expression differently in CD4+/CD25− and in CD4+/CD25+ cells in peripheral blood." (PMID 23251336, 2012). "This is exemplified by the ability of only IL-4 to differentiate naïve CD4+ T cells into Th2 cells or the non-redundant role of IL-13 in parasite expulsion, allergic inflammation and asthma." (PMID 23027612, 2012).